ATF6 (activating transcription factor 6)
Diseases named in the same sentence as ATF6 in open-access papers (continued):
Sharing a sentence is not in itself a finding about the gene and the disease.
colorectal cancer (21 papers, 2018 to 2026). A primary or metastatic malignant neoplasm that affects the colon or rectum. "Dysregulation of theses pathways, particularly ATF6α signaling, is closely associated with the occurrence of colorectal cancer." (PMID 40869379, 2025). "Given the critical role of Wnt signaling in driving stemlike function in colorectal cancer cells, we prioritized examining the impact of ATF6 silencing on gene sets associated with stemness and with several colonic tissue differentiation modules." (PMID 39324706, 2024). "Here, we used human colorectal carcinoma-derived HCT116 cells deficient in ATF6α and its relevant ATF6β, and found that ATF6α dimer and oligomer are both dimers, which we designated C618-dimer and C467-dimer, respectively." (PMID 31852864, 2020). "Together, these results indicate that the dependency of colorectal cancer lines on ATF6 may occur in the context of mutationally dysregulated Wnt signaling." (PMID 39324706, 2024). "By contrast, it promoted unbiased terminal differentiation and loss of viability of the PDM-272 colorectal cancer organoid, suggesting that the tumorigenic stem compartment may co-opt ATF6 to support Wnt signaling and cell pluripotency." (PMID 39324706, 2024). "However, LDB2 has been shown to inhibit liver cancer cell proliferation and migration, functioning as a tumor suppressor, while ATF6 has been linked to the induction of intestinal dysbiosis and immune activity associated with the development of colorectal cancer." (PMID 33075110, 2020). "DA has been reported to activate ER stress‐related proteins such as GRP78, endoplasmic reticulum calcium ATPase, PERK, IRE1 and ATF6 in both liver and colorectal cancer cells." (PMID 41521078, 2026). "With this level of promiscuity in downstream responses, not surprisingly, the selectivity between proliferation and cell death activation by ATF6 remains a mystery, especially in the case of colorectal cancer." (PMID 41301006, 2025). "We then verified that STK26 is a novel regulator of the 50 kDa ATF6 (p50) and prompts its stabilization by interacting with the 50 kDa ATF6 (p50), posing an important impact on the occurrence of colorectal cancer." (PMID 40869379, 2025). "Activation of ATF6 contributes to the occurrence of colorectal cancer and hepatoma and enhances tumor angiogenesis via the ATF6–EGF pathway." (PMID 40547943, 2025). "Here we show the clinical relevance of ATF6 in individuals with early-onset and late colorectal cancer, and link ATF6 signalling to changes in lipid metabolism and intestinal microbiota." (PMID 40890536, 2025). "To investigate the importance of ATF6 for colorectal cancer growth in vivo, we first validated the effectiveness of our Dox-inducible ATF6 shRNA approach in Colo201 tumor xenografts grown subcutaneously in mice." (PMID 39324706, 2024). "In this study, we show that ATF6 promotes colorectal cancer through an unexpected yet critical role in facilitating oncogenic Wnt signaling." (PMID 39324706, 2024). "This underscores the potential of ATF6-targeted therapies as novel chemosensitizers in colorectal cancer treatment." (PMID 39080273, 2024). "We constructed a tetracycline-selectable plasmid encoding a set of three Dox-inducible shRNAs that perturb ATF6 mRNA expression and stably transfected this plasmid into the human Colo201 and CCK81 colorectal cancer cell lines." (PMID 39324706, 2024). "Taken together, these results support the conclusion that ATF6 mediates colorectal cancer stemness by facilitating oncogenic Wnt and Myc signaling." (PMID 39324706, 2024). "Our findings uncover ATF6 as an unexpected facilitator of oncogenic Wnt signaling in colorectal cancer." (PMID 39324706, 2024). "Perhaps complementing our observations, previous work using cytomegalovirus early enhancer/chicken β-actin (CAG) promoter–driven ectopic overexpression of nATF6 uncovered an indirect role for ATF6 in colorectal cancer tumorigenesis." (PMID 39324706, 2024).
colorectal cancer (continued). "Despite the known interconnectedness between UPR branches, ATF6 interference did not promote compensatory activation of IRE1 or PERK, suggesting a more specialized role for ATF6 in colorectal cancer than seen in the canonical context of drug-induced ER stress." (PMID 39324706, 2024). "To examine the scope of ATF6 dependency in colorectal cancer models, we transfected a cohort of 12 additional human colorectal cancer lines with our inducible ATF6 shRNA construct." (PMID 39324706, 2024). "In colorectal cancer, phosphorylated ATF6 has been demonstrated to promote tumor development by inducing gut microbiome dysbiosis and activating the TIR domain-containing adapter-inducing interferon-β (TRIF)/STAT3 signaling cascade." (PMID 39080273, 2024). "ATF6 intervention reduces colorectal cancer cell and organoid viability by interrupting dysregulated Wnt signaling, identifying a novel facilitator and potential therapeutic target in colorectal cancer." (PMID 39324706, 2024). "Taken together, these results establish a significant ATF6 requirement for cell-cycle progression in these colorectal cancer lines." (PMID 39324706, 2024). "This study is the first to demonstrate that interference against ATF6 activity significantly reduces growth of diverse colorectal cancer models in vitro and in vivo." (PMID 39324706, 2024). "To assess the importance of ATF6 activity for colorectal cancer growth, we disrupted ATF6 expression in human colorectal cancer cell lines." (PMID 39324706, 2024). "Remarkably, all but the RKO cell line showed significant reductions in viability upon ATF6 silencing, indicating a broad ATF6 dependency in diverse colorectal cancer backgrounds." (PMID 39324706, 2024). "ATF6 silencing also led to stronger viability losses at low versus high seeding density in several additional colorectal cancer lines." (PMID 39324706, 2024). "All described ATF6 interventions were effective in various models at reducing cell viability and proliferation, providing the first evidence that ATF6 directly facilitates colorectal cancer growth." (PMID 39324706, 2024). "Genetic silencing or small-molecule inhibition of ATF6 blocked cell-cycle progression and reduced viability of several human colorectal cancer cell lines in vitro, and disrupted tumor progression in vivo." (PMID 39324706, 2024). "We examined the effect of interference with ATF6 activity on growth of human colorectal cancer cell lines and organoids." (PMID 39324706, 2024). "ATF6 knockdown also induced accumulation of p21 and p27 in several other ATF6-dependent colorectal cancer cell lines." (PMID 39324706, 2024). "We identify ATF6 as an important facilitator of oncogenic signaling in colorectal cancer, and as such, an exciting potential therapeutic target." (PMID 39324706, 2024). "Wnt-surrogate agonism in a Wnt ligand-dependent colorectal cancer organoid restored pathway activity and rescued growth under ATF6 blockade." (PMID 39324706, 2024). "We observed elevated ATF6 transcriptional activity in several cancers, including colorectal carcinoma." (PMID 39324706, 2024). "In this way, ATF6 plays a cancer-promoting role in colorectal cancer, prostate cancer, and other cancers." (PMID 37456776, 2023). "We found that CIP2A expression was positively correlated with ATF6 expression by analyzing publicly available RNA sequence data of patients with colorectal cancer (The Cancer Genome Atlas, TCGA)." (PMID 30063110, 2018). "Notably, ATF6 silencing disrupted both Wnt and Myc signaling, underscoring the dual potential of ATF6 for therapeutic targeting in colorectal cancer." (PMID 39324706, 2024). "The finding that ATF6 silencing inhibits cell-cycle progression and increases CDKi expression in colorectal cancer cells is consistent with recent evidence that ATF6 deletion in pancreatic β-cells during insulitis leads to cell-cycle arrest and increases the expression of CDKN1A." (PMID 39324706, 2024).
colorectal cancer (continued). "Earlier reports have ascribed roles for ATF6 in malignancy beyond colorectal cancer." (PMID 39324706, 2024). "Together, these results reveal a previously unrecognized intrinsic dependency in several colorectal cancer cell lines on ATF6, not only for in vitro growth but also for in vivo tumor progression, distinctly from earlier reports showing ATF6 requirement during experimentally induced stress." (PMID 39324706, 2024). "In colorectal cancer, ATF6 induces intestinal dysbiosis and tumorigenesis." (PMID 37456776, 2023). "ATF6 is also closely related to the occurrence of colorectal cancer." (PMID 34257653, 2021). "In addition, others have shown that ATF6 was related to reduced time of disease-free survival in colorectal cancer." (PMID 33178587, 2020). "Whether ATF6 is pro-survival or pro-apoptosis in any identified cancer is a topic of much debate as it is very context dependent, even within the same cancer-like colorectal cancers." (PMID 41301006, 2025). "Moreover, analysis of TCGA colorectal cancer data using the GEPIA2 online tool revealed that STK26 exhibits significant positive correlations with mRNA expression levels of ATF6 pathway downstream effectors (HSPA5, XBP1), clinically corroborating our experimental findings." (PMID 40869379, 2025). "Moreover, activated ATF6 could induce intestinal dysregulation and innate immune response and promote the occurrence of colorectal cancer." (PMID 34659567, 2021). "Upregulation of IRN1, PERK, ATF6, and CHOP demonstrates a strong ER stress response during colorectal cancer development." (PMID 39813534, 2025). "In summary, we found a new mechanism of the 50 kDa ATF6 (p50), regulated by STK26, in the development and progression of colorectal cancer." (PMID 40869379, 2025). "Supporting this latter idea, we discerned enriched expression of ATF6 and ER13 in the tumor stem/transit-amplifying cell compartment and diminished expression in differentiated epithelial cell lineages of colorectal cancer samples." (PMID 39324706, 2024). "Carfilzomib, targeting K-RAS(+) and cetuximab-resistant colorectal cancer, operates by upregulating UPR downstream CHOP and ATF6 expression, and enhancing apoptotic pathways through caspase-3/7 for anti-tumor activity." (PMID 39080273, 2024). "We uncovered elevated ATF6 activity based on the ER13 gene signature in several prevalent solid cancers, including colorectal cancer, on which we focused in this present study." (PMID 39324706, 2024). "For instance, overexpression of ATF6 and XBP1 reduces the proliferation and stemness of colorectal cancer cells by activating PERK signaling." (PMID 36890838, 2023). "ATF6α occurs as a monomer, dimer and oligomer in unstressed ER of the HCT116 diploid cell line derived from human colorectal carcinoma, similarly to the case of CHO cells." (PMID 31852864, 2020). "Moreover, we also elucidate how STK26, highly expressed in CRC, facilitates tumorigenesis via the ATF6 signal pathway, which provides a new perspective on the role of STK26 in colorectal cancer." (PMID 40869379, 2025). "RKO—the only colorectal cancer line we examined that was not sensitive to ATF6 knockdown —differs from the ATF6-dependent lines in that it lacks dysregulating mutations in the Wnt pathway." (PMID 39324706, 2024). "ATF6 dependency occurred in the absence of exogenous ER stressors, implicating ATF6 as a constitutive intrinsic facilitator of colorectal cancer growth." (PMID 39324706, 2024). "Taken together, our results demonstrate that GREM1 is an invasion-promoting factor via regulation of ATF6 and ATF4 expression in CRC cells, suggesting GREM1 may be a potential pharmacological target for colorectal cancer treatment." (PMID 35883579, 2022).
colorectal cancer (continued). "Additionally, as key players of UPR, activating transcription factor 6 (ATF6) upregulation and ATF4 downregulation activates PI3K/AKT/mTOR signaling but reduces Bone Morphogenetic Protein 2 (BMP2) signaling in colorectal cancer cells to enhance motility and invasion via EMT." (PMID 36890838, 2023). "Importantly, selective interference with ATF6 did not increase general ER stress, and inhibition of IRE1 or PERK had little impact on PDM-272 organoid growth, suggesting that the loss of colorectal cancer stemness upon ATF6 disruption is specific and independent of global ER stress." (PMID 39324706, 2024).
colon cancer (20 papers, 2012 to 2025). "Most importantly, immunohistochemical analysis of a tissue microarray from a colon cancer patient cohort showed that higher expression levels of ATF6 and CIP2A were associated with a trend toward poor prognosis." (PMID 30063110, 2018). "Similarly, immunohistochemical analysis of tissue microarray from a cohort of colon cancer patients showed that high expression levels of ATF6 were associated with a tendency for poor prognosis." (PMID 34659567, 2021). "The experimental use of combined Adriamycin and ATF6 inhibitors sensitizes colon cancer cells that are typically resistant to treatment to cytotoxic effects." (PMID 41301006, 2025). "Inhibits ATF6, demonstrating potential to sensitize colon cancer cells to cytotoxic effects in combination with Adriamycin; targets HSPA5-ATF6-CHOP axis." (PMID 41301006, 2025). "ATF6 is a UPR sensor that is located in the ER membrane, and that is associated with poor prognosis in Biliopancreatic and colon cancers." (PMID 35222510, 2021). "In connection with this, studies have shown that the expression of colon cancer oncogene CIP2A is positively correlated with the expression of ATF6, and ATF6, as a transcription factor, directly bind to the CIP2A promoter in turn." (PMID 34659567, 2021). "Because XBP1 and ATF6 have extensively overlapping sets of target genes, we set out to investigate both XBP1 and ATF6 signaling in colon cancer cells, and investigate the crosstalk of these branches with PERK- eIF2α20,29." (PMID 31227689, 2019). "In the present study, we found that in patients with colon cancer, either ATF6 or CIP2A protein overexpression were negatively correlated to the OS rates." (PMID 30063110, 2018). "To determine the clinical significance of ATF6 and CIP2A expression in colon cancer, we analyzed the relationship between ATF6 protein expression and various clinicopathological parameters in a total of 165 patients with colon cancer." (PMID 30063110, 2018). "The results indicated that CIP2A sustains the survival of colon cancer cells through ATF6 under ER stress conditions." (PMID 30063110, 2018). "ATF6 was shown to sustain the expression of oncogenes such as BRCA1 or CIP2A (in vitro data in human colon cancer cell lines CaCO2, and SW480), as well as prevent DNA damage and to improve cancer cell viability, as observed in RKO and HCT116 colon cancer cell lines." (PMID 36902344, 2023). "Interestingly, we have also shown that ATF6 inhibition sensitized stressed cancer cells to the cytotoxic effect of Adriamycin, a drug widely employed for the treatment of colon cancer." (PMID 35752616, 2022). "We first confirmed that ATF6 inhibition by ceapinA7 could further reduced cell survival in DPE-treated RKO colon cancer cells, as previously reported." (PMID 35752616, 2022). "Indeed, ATF6 incidence is increased in many colon cancer patients, with close to 11% of CRC patients showing an increase in ATF6." (PMID 35174040, 2022). "However, the role of ATF6 in colon cancer and the detailed mechanism by which ATF6 regulates colon cancer survival are poorly understood." (PMID 30063110, 2018). "Future research should incorporate comprehensive protein‐level assessments of PERK, ATF6, IRE1α, CHOP, and associated effectors to reinforce the in silico and in vitro findings and to elucidate the modulatory effects of 4‐PBA on ER‐stress within colon cancer models." (PMID 40953838, 2025). "All together this study suggests that targeting ATF6 may not only potentiate the cytotoxic effect of drugs triggering ER stress but may render colon cancer cells more sensitive to Adriamycin and possibly to other DNA damaging agents used to treat colon cancer." (PMID 35752616, 2022). "This study shows for the first time that ATF6 sustains the expression level of BRCA-1 and protects colon cancer cells from the cytotoxic effect of ER stressors DPE and Thapsigargin." (PMID 35752616, 2022).
colon cancer (continued). "ER stress is reported to induce 5-FU resistance in colon cancer, and the silencing of GRP78, ATF6, ERK, or AKT is indicated to increase the sensitivity of colon cancer cells to 5-FU." (PMID 37304412, 2022). "Taken together, our results show that ER stress‐related ATF6 upregulates CIP2A and contributes to the prognosis of colon cancer." (PMID 30063110, 2018). "In conclusion, our present study provides evidence of linkage between ER stress and CIP2A, while conditional ER stress‐related ATF6 upregulates CIP2A and contributes to the prognosis of colon cancer." (PMID 30063110, 2018). "Due to the importance of ATF6 signaling in the survival of cancer cells, we next evaluated the effect of CIP2A knockdown in colon cancer cells." (PMID 30063110, 2018). "Mechanistically, we found that ATF6 directly bound to the CIP2A promoter and induced CIP2A gene expression, which contributed to colon cancer cell survival." (PMID 30063110, 2018). "We further investigated the prognostic value of ATF6 and CIP2A expression, independently, in patients with colon cancer and CRC." (PMID 30063110, 2018). "We have previously shown that the inhibition of ATF6 by ceapinA7 exacerbated ER stress induced by 3,4-dihydroxyphenyl ethanol (DPE), an antioxidant compound contained in the olive oil, increasing its cytotoxic effect against colon cancer cells." (PMID 35752616, 2022). "However, the new finding of this study is that it shows for the first time that ATF6 arm of UPR plays a key role in DNA repair, by sustaining BRCA-1 expression in colon cancer cells undergoing ER stress." (PMID 35752616, 2022). "ATF6 is a crucial regulator of the UPR pathway that is involved in coagulation, and that has been identified as a poor prognosis factor in biliopancreatic carcinoma and colon cancer." (PMID 35222510, 2021). "In this study, we evaluated the correlation between ATF6 and CIP2A in patients with colon cancer." (PMID 30063110, 2018). "The clinicopathological characteristics in multivariate analysis by Cox regression, ATF6, were not a prognostic factor for survival, while CIP2A was independently associated with survival in patients with colon cancer and CRC." (PMID 30063110, 2018). "While ATF6-IHC staining was negative in normal colonic epithelial cells, it was positive in the cytoplasm and nucleus of the colon cancer cells." (PMID 28884228, 2018). "We found that the expression of ATF6 was positively correlated with the expression of CIP2A not only in patients with colon cancer but also in both the colon cancer cell line and the immortalized normal cell line under ER stress." (PMID 30063110, 2018). "Increased level of GRP78, which was observed in colon cancer cell functions as chaperone may dissociate from its conformational binding state of the transmembrane receptor protein kinase RNA like endoplasmic reticulum kinase (PERK), IRE1 and activating transcription factor 6 (ATF6)." (PMID 31108984, 2019). "However, ATF6 protein expression was not correlated with other clinicopathological parameters such as age, gender, tumor location, pathology, tumor grade, or lymphovascular involvement in patients with colon cancer and CRC." (PMID 30063110, 2018).